SIRT3 (sirtuin 3)
Diseases named in the same sentence as SIRT3 in open-access papers (continued):
Sharing a sentence is not in itself a finding about the gene and the disease.
cancer (continued). "Meanwhile, related studies have shown that SIRT3, SIRT4 and SIRT6 also inhibit the Warburg effect and exert anticancer effects by regulating components of the phosphatidylinositol-3 kinase pathway, which is central to cancer metabolism." (PMID 40292294, 2025). "Sirtuins, including SIRT1, SIRT3, and SIRT4, are master regulators that can exert either an activating or inhibitory effect on immune activation, depending on the cellular context and cancer type." (PMID 41425553, 2025). "Scientists have demonstrated that mice without SIRT3 have significantly shorter lifespans and spontaneously develop cancer, metabolic syndrome, cardiovascular disease, and neurodegenerative diseases." (PMID 38294557, 2024). "Furthermore, SIRT3 deacetylates and activates the mitochondrial pyruvate dehydrogenase complex (PDC), inhibiting glycolysis and promoting apoptosis in cancer cells." (PMID 39479446, 2024). "Mitochondrial sirtuins, (Sirtuin) SIRT3, SIRT4, and SIRT5, play crucial roles in cancer metabolism." (PMID 38331199, 2024). "Unlike SIRT3 inhibitors, SIRT3 activators for cancer treatment are still in the early stages of development." (PMID 38773972, 2024). "That is why it is not surprising that SIRT3 is involved in aging, neurodegeneration, liver disease, kidney disease, heart disease, and other metabolic diseases, and in cancer, too." (PMID 37345199, 2023). "Together with the fact that Sirt3 interacts with and deacetylates LONP1, Sirt3 may limit the transformation procedure in cancer initiation by maintaining appropriate lysosomal degradation of LONP1 through K63-ubiquitination pathway." (PMID 36739437, 2023). "Again, to provide preliminary indications of the clinical relevance of our identified mechanism of metabolic regulation in cancer involving PROX1, SIRT3, and EZH2, we examined the correlations between these protein expression levels in CRC patient tissues and clinical parameters and prognosis." (PMID 36594098, 2023). "However, further studies are needed to investigate the role of UHRF1 in the SIRT3/SOD2-Akt signaling pathway, which regulates various critical cellular processes required for cancer cell survival." (PMID 37630248, 2023). "It is crucially demonstrated that SIRT3 overexpression is sufficient to prevent HIF-1 stabilization under hypoxia and to suppress carcinogenesis, revealing a unique role for SIRT3 in the upkeep and development of cancer." (PMID 37646973, 2023). "Nevertheless, cancer cell lines derived from rectal sites are not representative of the overall expression profile of SIRT3 in CRC." (PMID 36594098, 2023). "Sirtuin 3(SIRT3)is the most talked about Sirtuin family member in recent times (a family of NAD+-dependent deacetylases that regulate signaling pathways involved in cellular proliferation and differentiation, metabolism, response to stress, and cancer." (PMID 37362244, 2023). "However, LINC00922 overexpression blocked SIRT3 recruitment to the ETS1 promoter and then increased ETS1 transcription by increasing H3K27cr level in this region, ultimately promoting cancer metastasis." (PMID 37789393, 2023). "For example, studies reveal that mice lacking SIRT3 have significantly shortened lifespans and spontaneously develop several aging-related diseases, including cancer, metabolic syndrome, cardiovascular disease, and neurodegenerative diseases." (PMID 36010672, 2022). "Although reviews on the dual role of SIRT3 in cancer have been summarized and published, there is currently no systematic review on cancer metastasis and drug resistance about the role of SIRT3." (PMID 35832551, 2022).
cancer (continued). "SIRT3 is also the major deacetylase of methylenetetrahydrofolate dehydrogenase 2 (MTHFD2), promoting its activity and determining a boost in cell proliferation and cancer development." (PMID 35328633, 2022). "SIRT3 suppression leads to increased mitochondrial ROS production, decreased PGC-1α expression and mitochondrial function, and, subsequently, to higher sensitivity to anti-cancer drugs." (PMID 34769108, 2021). "SIRT3 (Sirtuin 3, NAD-Dependent Protein Deacetylase Sirtuin-3, Mitochondrial) is a crucial mitochondrial protein, known to eliminate ROS, inhibit apoptosis, and prevent the formation of cancer cells." (PMID 34769108, 2021). "On the other side, SIRT3 knock-down leads to decreased SOD2 expression and activity, decreased mitochondrial activity, and increased apoptosis, with further improved sensitivity to anti-cancer drugs." (PMID 34769108, 2021). "Our findings reveal an unknown regulation axis of cisplatin-SIRT3-MTHFD2 in redox homeostasis and suggest a potential therapeutic strategy for cancer treatments by targeting MTHFD2." (PMID 32811824, 2020). "Moreover, anti-cancer agent etoposide-induced genotoxic-mediated cancer cell apoptosis has been shown to correlate with both SIRT1 and SIRT3 over-expression." (PMID 32252351, 2020). "A search of the DepMap CRISPR database of gene knockout for SIRT3/SAP18/SIN3 across hundreds of cancer cell lines identified SAP18/SIN3 but not SIRT3 as a critical survival gene." (PMID 33273692, 2020). "More regrettably, there are no satisfactory SIRT3 activators or inhibitors that have been developed successfully for cancer therapy, which makes recognition of SIRT3 as a druggable target in cancer more difficult and questionable." (PMID 32724473, 2020). "LncRNA-TUG1 via miR-145/Sirt3/GDH axis could regulate glutamine metabolism and promote cancer progression." (PMID 33123468, 2020). "SIRT3 regulates fatty acid oxidation via the deacetylation and activation of long chain acyl-CoA dehydrogenase (LCAD) enzyme, opposite to HIF1α that suppresses fatty acid oxidation to facilitate cancer progression." (PMID 32117717, 2020). "It has been reported that SIRT3 is able to induce growth arrest and apoptosis in both cancer cells and in non-cancer cell lines." (PMID 31474877, 2019). "SIRT3 was also reported to have a dual function in tumorigenesis, due to its deacetylation activity of mitochondrial proteins such as SOD2, IDH2, and FOXO3a, and inhibition of mitochondrial ROS production and cancer cell proliferation." (PMID 30761005, 2019). "On the contrary, SIRT3 exhibited oncogenic properties in the context of HFD-induced tumorigenesis, suggesting that SIRT3 inhibition may mitigate the cancer-promoting effects of HFD." (PMID 31970087, 2019). "It has been proposed that mitochondrial proteins, such as SIRT3 and SIRT4, may function as critical regulators at the crossroads between metabolism, aging, and cancer." (PMID 26785117, 2016). "The meta-analysis found that there was no detectable relation between SIRT3 expression and prognosis in various cancer patients with the pooled HR of 1.05 (95% CI = 0.51–2.16, P = 0.89)." (PMID 27483432, 2016). "In noncancerous samples the majority (56%, 19/32) was SIRT3-high scored, whereas in carcinoma samples, the percentage of SIRT3-high scored plummeted to 22% (16/74) with the SIRT3-low scored rising up to 58% (43/74)." (PMID 26317998, 2015). "SirT3 has been reported as a novel key coordinator of UPR and serves as a mechanism of adaptation through orchestrating antioxidant machinery and mitophagy, implying its contrasting dual roles in cancer development." (PMID 32309542, 2014). "Based on these results, it has been proposed that mitochondrial proteins, such as SIRT3 and SIRT4, may function as critical regulators at the crossroads between metabolism, aging, and aging-related human illnesses such as cancer." (PMID 25332769, 2014).
cancer (continued). "Furthermore, downregulation of SIRT3 arrested OSCC cell proliferation and sensitized cancer cells to radiation and chemotherapy treatments." (PMID 23272146, 2012). "In addition, SIRT3 knockout mice were also hypersensitive to cardiac stress induced by transverse aortic constriction (TAC), and to cancer." (PMID 21386135, 2011). "In addition to having major implications for the oxidative stress theory of aging, the latest findings connecting SIRT3 and oxidative stress have also provided illumination to long-standing questions regarding calorie restriction (CR) and may lead to a novel way of treating cancer." (PMID 21307404, 2011). "In summary, our present study reveals a novel function of PROX1 in cancer cell metabolism, i.e., PROX1 recruits EZH2 to the SIRT3 promoter and represses SIRT3 transcription, which may represent the molecular mechanism underlying the observed biological consequences." (PMID 36594098, 2023). "Sirtuin 3 (SIRT3)-dependent ROS production and HIF-1α stabilization upregulates the expression of glucose transporter GLUT1 and lactate transporter monocarboxylate transporter-4 (MCT4) in CAFs, thereby shuttling lactate from CAFs to cancer cells to promote anabolic processes and cell growth." (PMID 35884382, 2022). "In the pathway of central carbon metabolism in cancer, SIRT6 could directly inhibit hypoxia-inducible factor 1α (HIF-1α), and SIRT3 could inhibit HIF-1α by repressing HIF-1 signaling, which then affected metabolic process such as glycolysis and tricarboxylic acid (TCA) cycle." (PMID 35136826, 2022). "Therefore, we propose that SIRT3 activation in MPNST cells is antineoplastic at least in part by re-establishing SDH activity and counteracting HIF1α stabilization, as we have observed in xenografted cancer cells." (PMID 35393510, 2022). "Interestingly, SIRT3 is known to deacetylate and increase PDH activity in cancer cells." (PMID 33937086, 2021). "Our data indicates that active ATM signaling is indeed necessary for mitochondrial structural integrity in cancer cells similar to normal physiological conditions and SIRT3 stimulation does not alleviate structural changes in mitochondria in ATM deficient DLBCL cells." (PMID 33273545, 2020). "So far, a connection between SIN3/SAP18 and SIRT3 not been established, nor is it known if such interaction impacts cancer and whether it exploited therapeutically." (PMID 33273692, 2020). "Several studies show that mice lacking SIRT3 show no important affections under basal conditions, although after fasting, exercise or calorie restriction these mice develop several diseases, including some types of cancer." (PMID 28704962, 2017). "Therefore, further study elucidating the molecular pathogenesis of the multi-facet Sirt3 in HCC may lead to more effective and specific therapies against this intractable cancer." (PMID 24774224, 2014). "Importantly, SIRT3 has delactylation activity, the removal of lactylation from the non-histone proteins on Cyclin E2 (CCNE2), a key cell cycle protein reported to be essential for cancer progression, is catalyzed by SIRT3 to suppress the proliferation, migration, and invasion of cancer cells." (PMID 40164592, 2025). "This does not mean that SIRT3 is not a suitable candidate for anti-cancer therapy development, but its application may be limited or restricted to those tumors that have reprogrammed their mitochondrial machinery towards a “Warburg phenotype” and may benefit from a rewire of their metabolism." (PMID 37345199, 2023). "However, how SIRT3 is involved in cancer is still not fully elucidated." (PMID 37507016, 2023). "Finally, several studies also indicate that the acetylation statuses of SIRT3 substrates like acetyl-CoA synthetase, GDH, long-chain acyl-CoA dehydrogenase (LCAD), succinate dehydrogenase, and mitochondrial ribosome subunit MRPL10 are frequently altered in human cancers." (PMID 25332769, 2014).
cancer (continued). "Moreover, the usual acetylation of proteins may be retarded in highly glycolytic cancer cells; hence, no SIRT3-mediated deacetylation would be required." (PMID 22675360, 2012). "Unlike 4-BR modulating SIRT3, resveratrol stimulates SIRT1 activity and expression to inhibit cancer stemness." (PMID 35723384, 2021). "Despite the novelty of these new 1,4-dihydropyridine Sirt3 activators, the lack of animal model testing demonstrates the current superiority of ADTL-SA1215 as the Sirt3 activator of choice for probing the roles of Sirt3 in cancer." (PMID 38474697, 2024). "Therefore, the observation that in the absence of SIRT3, the activity of SOD2 is abolished, is a likely reason for the elevated ROS levels in cancer cells." (PMID 24955214, 2014).
cardiovascular diseases (63 papers, 2015 to 2025). "SIRT3 deacetylation regulates mitochondrial function and is associated with numerous age‐related diseases, such as cardiovascular disease and neurodegenerative diseases." (PMID 39138637, 2024). "SIRT3 can regulate mitochondrial function and is associated with many aging‐related diseases such as cardiovascular disease and neurodegenerative disease." (PMID 39138637, 2024). "Experiments with SIRT3 have also found that SIRT3 ablation is associated with cardiovascular diseases." (PMID 36187338, 2022). "Previous studies have also shown that mitochondrial disorders mediated by Sirt3 deficiency are involved in the development of human cardiovascular diseases." (PMID 34095262, 2021). "Current evidence associates impaired SIRT3 activity with higher risk of aging-associated illnesses like cardiovascular disease." (PMID 32499759, 2020). "Abnormal function of SIRT3 in pathophysiological processes is considered as the underlying mechanism of cardiovascular diseases." (PMID 32499759, 2020). "Since cardiovascular diseases, particularly HF, are age-associated diseases, it is important to study the potential mechanism by which SIRT3 can mediate the cardiac-related effects of CR on lifespan." (PMID 30131726, 2018). "We have reported Sirt3-mediated protection from accelerated weight gain and a decline in metabolic flexibility, two important risk factors of human cardiovascular diseases." (PMID 27071400, 2016). "Recently, Sirt3 deficiency has been reported to accelerate the development of the metabolic syndrome, a cluster of hallmark risk factors for cardiovascular disease." (PMID 27071400, 2016). "Simultaneously, cardiovascular disease risk factors may lead to reduced SIRT3 level." (PMID 40893347, 2025). "Although Sirt3 deacetylation activity has been demonstrated and thousands of substrates have been examined by multitissue quantitative proteomics, bioinformatics analysis, and studies on biochemical effectiveness, very few functions of Sirt3 are associated with cardiovascular disease." (PMID 40800583, 2025). "Clinical studies have shown that the expression of SIRT3 decreases with age, consistent with an increase in the incidence of cardiovascular diseases." (PMID 40893347, 2025). "Lifestyle change is one of the important treatment modalities for cardiovascular disease, and changing an unhealthy lifestyle helps to regulate SIRT3 expression, which plays a role in the prevention and management of cardiovascular disease." (PMID 41276460, 2025). "Studies have shown that diets high in sugar, fat, and salt all downregulate SIRT3 levels, leading to the development of cardiovascular disease; therefore, a “three lows” diet can minimize cardiovascular damage." (PMID 41276460, 2025). "This innovative discovery not only deepens the understanding of the function of SIRT3 but also provides new clues for targeted therapy of cardiovascular diseases." (PMID 41276460, 2025). "In conclusion, lifestyle improvement can help elevate SIRT3 levels and play a role in alleviating cardiovascular disease, which is likewise important for improving DCM." (PMID 41276460, 2025). "Through maintenance of mitochondrial function, Sirt3 is involved in aging and neurodegenerative and cardiovascular diseases; significant differences between sexes should be accounted for in future research." (PMID 38612678, 2024). "Investigating how age‐related changes modulate the role of endothelial SIRT3 could provide deeper insights into age‐specific therapeutic strategies and improve our understanding of the association between aging and vascular function and its impact on cardiovascular diseases." (PMID 39425510, 2024). "Since sirtuin 3 (SIRT3) exerts cardioprotective effects in cardiovascular diseases, including SIMI, SIRT3 expression in H9C2 cells was detected." (PMID 37057132, 2023).